CD4 (CD4 molecule)
Diseases named in the same sentence as CD4 in open-access papers (continued):
Sharing a sentence is not in itself a finding about the gene and the disease.
sarcoma (80 papers, 2010 to 2025). A usually aggressive malignant neoplasm of the soft tissue or bone. "In recent work investigating the role of neoantigen-specific CD4+ T cells in a murine sarcoma model, epitopes derived from a mutated integrin subunit, also a membrane-bound protein, were eluted from MHC-II on CIITA-transduced tumor cells." (PMID 36512410, 2023). "In a recent publication using a mouse methylcholanthrene-induced sarcoma model, in which the mutations recognized by CD4+ and CD8+ T cells were distinct, coexpression of those mutations in the same tumor cells was required for tumor rejection by immunotherapy." (PMID 35439168, 2022). "Additionally, the CIBERSORT analysis demonstrated the strong association of high ZFP36L2 expression with macrophages and CD4+ T cells, particularly in sarcomas." (PMID 39767767, 2024). "Matrigel and BME are BMEs obtained from a mouse sarcoma, and therefore it is possible that murine CD4+ T cells are more sensitive to the biochemical cues present in these gels than human T cells." (PMID 40837221, 2025). "Some studies have demonstrated that CD4+ T cells in infiltrating lymphocytes occupying core proportions in the microenvironment were related to prognosis in sarcomas." (PMID 38635069, 2024). "Specifically, chromophobe renal cell carcinoma, sarcoma, and skin cutaneous melanoma presented significance in multiple cell types, namely in CD4+ T lymphocytes, gammadelta T lymphocytes, and NK cell populations." (PMID 36612301, 2023). "What’s more, we also confirmed that the high expression of NCAP family members was significantly related to the immune infiltration level of CD4+ T cells and macrophages, which provided a new insight for the effectiveness of future immunotherapy for sarcoma." (PMID 37192046, 2023). "The expression of NCAPs in sarcoma was significantly related to the low infiltration level of macrophages and CD4+ T cells." (PMID 37192046, 2023). "According to TIMER, the expression level of CENPF was positively correlated with tumor purity or the infiltration level of B cells, while negatively correlated with the infiltration level of CD4+ T cells or macrophages in sarcomas." (PMID 37108172, 2023). "The mean percentage of CD4+ T cells in the peripheral blood of sarcoma patients (20.18%) was lower (p = 0.037) than that of normal controls (27.76%)." (PMID 36005179, 2022). "Although we were able to show that there is a reduction (p < 0.05) of CD4+ T cells in the peripheral blood of sarcoma patients compared to healthy volunteers, we acknowledge in retrospect that this study has several limitations." (PMID 36005179, 2022). "In this study, the results show that the percentage of total CD4+ T cells was lower (p < 0.05) in sarcoma patients compared to healthy volunteers." (PMID 36005179, 2022). "Our proposed strategy to enrich for human tumor–reactive CD4+ Th cells is supported by a previous study in a mouse sarcoma model showing that neoantigen-reactive CD4+ Th cells found in the tumor expressed both PD-1 and ICOS." (PMID 35439168, 2022). "Coexpression of PD-1 and ICOS had previously been shown to mark neoantigen-reactive CD4+ Th cells in a murine sarcoma tumor model." (PMID 35439168, 2022). "The CD4/CD8 ratio of sarcoma TILs ranged from 0.01–550 in “high-density” populations, and 0.1–927 in “low-density” populations." (PMID 35158816, 2022). "In regard to CD8, CD4, and Treg estimates, hot-tumors across all four sarcoma subtypes were broadly similar to hot-tumors in immunotherapy-responsive cancers." (PMID 35558159, 2022). "The results substantiated that sarcoma patients with elevated CD4+ T cell and neutrophil infiltration levels have better survival outcomes." (PMID 36092720, 2022). "Sarcoma subtypes were also broadly similar to immunotherapy responsive cancers in regard to the trends observed for Treg, CD4-effector, B cell, and NK cell estimates between hot and cold tumors." (PMID 35558159, 2022).
sarcoma (continued). "In our sarcoma study, CD4+ T helper cells comprised 33%–43% of total CD3+ T cells in all treatment groups." (PMID 36227698, 2022). "Flow cytometer analysis was performed on blood samples from 26 sarcoma patients and 10 healthy controls to identify the levels of CD4+ T-cells and T-reg cells." (PMID 36005179, 2022). "CD4+ T cells are found to be required for immune checkpoint blockade response in the context of a poorly immunogenic T3 sarcoma cell line engineered to express MHCII antigens." (PMID 35565302, 2022). "By searching TIMER web tool, we also found that the IFNB1 mRNA expression level was positively correlated with the infiltration levels CD8+ T cells, CD4+ T cells, and CD4+ Th2 cells in sarcoma." (PMID 35662245, 2022). "CBX genes were positively correlated with the infiltration of immune cells, including CD8+ T cells, CD4+ T cells, B cells, macrophages, neutrophils, and dendritic cells, in sarcoma." (PMID 34046352, 2021). "We also found that the CBX family was positively correlated with the infiltration of immune cells, including CD8+ T cells, CD4+ T cells, B cells, macrophages, neutrophils, and dendritic cells, in sarcoma." (PMID 34046352, 2021). "TH1 polarized CD4+ T cells offer long-term protection against tumor re-challenge and is required for response to immune checkpoint blockade therapy in a T3 murine sarcoma model." (PMID 34012451, 2021). "Another study using a mouse model for sarcoma also supports a role of CD4+ T cells to induce dormancy in cancer cells and tumor relapse." (PMID 34012451, 2021). "Taken together, these findings stimulate the development of new strategies able to strengthen the generation of memory CD4+ T cells and exploit the anti-tumour functions of B lymphocytes to improve the control of sarcomas." (PMID 33207697, 2020). "Both matrixes are generated from murine sarcoma and therefore are compose of great murine antigen amounts, which can activate immune cell subtypes such as CD4+ T cells." (PMID 33362787, 2020). "Due to the role of Tregs in suppressing the activity of CD8+ and CD4+ T cells, the maintenance of an equilibrium state was influenced by higher CD8+/Treg cell ratio, which was also associated with improved survival of sarcomas mice." (PMID 31297335, 2019). "Correlation analyses using sarcoma data of TCGA showed that the expression of IFN-γ was positively correlated with that of CD4 and CD45RO, but strong positive correlations were observed with CD3E and CD8A expression." (PMID 29896199, 2018). "The anti-tumor effect of IL-12 on sarcomas or adenomas, which are considered immunogenic cancers, is mediated by CD4+ or CD8+ T cells." (PMID 27549240, 2016). "We observed that radiation rapidly activates NF-κB in human sarcoma cells and increases both CD4+ and CD8+ T cells in the tumor microenvironment." (PMID 27014915, 2016). "Sarcoma patients had increased expression of CTLA-4, a T-cell inhibitory receptor, on both CD4 (38 % sarcoma vs. 16 % HV; p = 0.05) and CD8 T cells (37 % sarcoma vs. 12 % HV; p = 0.05) as compared to HV." (PMID 26286851, 2015). "CD4 depletion in sarcoma bearing mice compromised the NLGP mediated tumor growth restriction particularly at a later stage (data not shown)." (PMID 23326300, 2013). "In the S180 sarcoma, while the infiltrating CD4+ T-cells and CD19+ B-cells were significantly lower in tumors with RBP-J-/- DCs, the decease of CD8+ T-cells and NK-cells appeared not so impressive." (PMID 20420708, 2010). "Ameliorates local sarcoma and induces proliferation of CD4+ T cell response." (PMID 37822929, 2023). "The CD4+ T cells were calculated as a percentage of the lymphocyte population and the Treg cells were calculated as a percentage of the CD4+ T-cell population in sarcoma patients or normal controls." (PMID 36005179, 2022).
sarcoma (continued). "Through the common results of the two analysis methods, we found that the degree of immune cell infiltration in patients with sarcoma with high m6A score group was lower than that in patients with low m6A score groups (e.g., dendritic cells, macrophages, CD4+ T cells, and neutrophils)." (PMID 34979500, 2022). "Furthermore, we compared the ratios of immune-stimulatory to immune-inhibitory signatures (CD8 + /CD4 + regulatory T cells) among the sarcoma subtypes." (PMID 35093080, 2022). "Hence, this study was undertaken to compare peripheral CD4+ T cells and Treg cells and levels of a selection of T-cell-related cytokines in sarcoma patients with healthy controls." (PMID 36005179, 2022). "This study is a pilot project to investigate whether there are differences in the proportion of CD4+ T cells in sarcoma patients and healthy individuals using several research approaches." (PMID 36005179, 2022). "Thus, a lower percentage of CD4+ T cells observed in sarcoma patients compared to normal controls also indicates reduced T-cell-mediated anticancer immune response in patients with sarcomas." (PMID 36005179, 2022). "To determine whether our findings were relevant in the context of non-TCR transgenic T cells, we evaluated the role of IL-2 in the acquisition of cytotoxic activity by CD4+ T cells in MCA205 sarcoma, which is known to respond to αCTLA-4 monotherapy." (PMID 31924474, 2020). "More recently, a NCI study (NCT00923351) reported restoration of CD4+ T cell counts by CYT107 treatment in pediatric sarcoma patients treated by a combination of standard antineoplastic therapy followed by autologous lymphocytes and tumor lysate/KLH-pulsed dendritic cell vaccinations." (PMID 30922400, 2019). "Furthermore, CTLA-4 upregulation in different intratumoral T-cell populations, such as CD4+CD25highFoxp3+ Tregs, CD4+, and CD8+ T cells, has been associated with abnormal cytokine signaling and poor prognosis in B-ALL and aggressive pediatric sarcoma patients." (PMID 38927907, 2024). "Furthermore, a higher ratio of CD8+/CD4+ T cells was observed in mice with dormant sarcomas compared with mice with progressing sarcomas, suggesting that increased CD8+/CD4+ T cells ratio may contribute to maintain an equilibrium state and cancer dormancy." (PMID 31297335, 2019). "The cancer resistance against S180 sarcoma cells could be transferred to susceptible non-resistant BALB/c mice as well as C57BL/6 mice after depletion of both CD4+/CD8+ leukocytes and B-cells from SR/CR mice." (PMID 23555858, 2013). "CD4 and CD8 quantification will require frozen sections of sarcomas and potentially flow cytometry of disaggregated tumours." (PMID 39462771, 2025). "CC-3 treatment resulted in significant and sustained activation of CD4+ and CD8+ T cells with all sarcoma subtypes tested." (PMID 38765008, 2024). "A pilot study reported a remarkable decrease in the number of CD4+ T-cells (p = 0.037) and the level of TNF (p = 0.004) in sarcoma patients." (PMID 38338920, 2024). "SMC4 was found to be significantly related to poorer OS in sarcoma patients with reduced eosinophils, CD8+ T-cells, CD4+ memory T cells, B cells, basophils, natural killer T-cells, regulatory T-cells and type 2 T-helper cells." (PMID 36719264, 2023). "In sarcoma, the expression of SMC4 was correlated with the infiltration of B cells and CD8+ T cells but negatively correlated with the immune infiltration of CD4+ T cells and macrophages." (PMID 36719264, 2023). "Sarcoma (SARC) showed significant p-values in its total lymphocyte (p = 0.2290), NK cells (p = 0.1979), Tgammadelta cells (p = 0.07291), and CD4+ (p = 0.6344) cell populations." (PMID 36612301, 2023). "This is highlighted in a recent report in which a single mutation among 24 (4.2%) predicted for MHC II presentation was found to be a target of CD4+ T cells and was capable of enhancing prophylactic CD8+ T cell immunity in a highly immunogenic sarcoma model." (PMID 37655661, 2023).
sarcoma (continued). "According to TIMER data, EIF4G3, and NCBP1 were negatively connected with CD4+ T cells and dendritic cells, however, EIF4A1 and WDR4 were not substantially correlated with immune cell infiltration in sarcomas." (PMID 36816047, 2023). "Next on the list, sarcoma (SARC) was selected as the second BCC “relative”, specifically regarding its total lymphocytes, Tgammadelta, NK, and CD4 cells scores." (PMID 36612301, 2023). "Our study showed reduced CD4+ T cells, IFN-γ, and TNF-α and identification of peripheral immune related genes in sarcoma patients compared to healthy controls, indicating reduced anti-cancer immunity in these patients." (PMID 36005179, 2022). "Next, immune infiltration in sarcoma was analyzed by TIMER, and the results showed that the expression of PLOD2 in sarcoma was correlated with B cells, CD8 positive T cells, CD4 positive T cells, macrophages, neutrophils and DC cells." (PMID 36276118, 2022). "Survival analysis by TIMER showed that the expression of CD4 positive T cells, Neutrophil and PLOD2 were related to the clinical prognosis of sarcoma patients." (PMID 36276118, 2022). "A marked reduction in the percentage of CD4+ T-cells (p = 0.037) and levels of TNF-α (p = 0.004) and IFN-γ (0.010) was observed in sarcoma patients." (PMID 36005179, 2022). "Significant positive correlation between gene expression of PTEN and CD4 was observed in most of the tumor types except for low-grade glioma (LGG), sarcoma (SARC) and thyroid carcinoma (THCA)." (PMID 33874915, 2021). "The correlations between the expression of ST2 and CD4, CD8A, and CD33, and between IL-33 and CD8A and CD45RO were then validated by analysis using GSE2719 or GSE 967 GEO datasets of sarcoma." (PMID 29896199, 2018). "We have identified several immune phenotypes that are altered in pediatric sarcomas including elevated CD14+ HLA-DRlo/neg cells, elevated CTLA-4+ T cells, and decreased CD4 T cells." (PMID 26286851, 2015). "In light of this, the TIMER2 database was utilized to investigate the possibility of a correlation between CX3CL1 and CD4+ T cell infiltration were observed in colon adenocarcinoma (COAD), LIHC, GBM, PRAD, KIRC, LUAD, HNSC, THCA, and sarcoma (SARC) based on the EPIC and TIMER algorithms." (PMID 37153002, 2023). "The prognostic impact of TILs in sarcoma is not fully clear, though some studies suggest better survival rates in patients with higher infiltration levels of CD4+ TILs and CD8+ TILs." (PMID 37190214, 2023). "This study aimed to investigate the level of CD4+ T cells and forkhead box protein P3+ (FoxP3+) Treg cells, as well as T-cell-related-cytokines such as TNF-α, IFN-γ, IL-17A, and TGF-β1 in the peripheral blood of sarcoma patients." (PMID 36005179, 2022). "Furthermore, it has been reported that the infiltration of CD4 + and CD8 + T cells can be regarded as a reliable prognostic factor in sarcomas." (PMID 34631703, 2021). "The expression of a dominant negative Pparg construct (dnPparg) in myeloid cells resulted in an increase in myeloid derived suppressor cell (MDSC) accumulation, increased inflammatory cytokine production, reduced CD4+ and CD8+ T-cells, and spontaneous carcinoma and sarcoma formation." (PMID 31212694, 2019). "However, in a similar sarcoma model using TDLN which were anti-CD3/anti-CD28 activated, CD4 cells were more potent effector cells than CD8 cells." (PMID 26090481, 2015). "In fact, sarcomas induced by MCA increase the frequency of Treg (FoxP3+ of CD3+, CD4+ cells, Sup." (PMID 26076008, 2015). "Increased expression of the inhibitory T cell receptor CTLA-4 on CD4 and CD8 T cells in sarcoma patients may have direct implications for immune therapy." (PMID 26286851, 2015). "Candidiasis was the only significant predictor of immune suppression measured as CD4 < 350 cells/mm3, (OR = 2.56, 1.52-4.30, p < 0.001), The PPV of OHL, kaposi sarcoma, melanotic hyperpigmentation and candidiasis were 47.4%, 41.9%, 32.2% and 48.2% respectively." (PMID 25432363, 2014).
sarcoma (continued). "In examining the status of regulatory cells, we have observed no significant changes in CD4+CD25+Foxp3+ T regulatory cells in various immune compartments in day 21 NLGP-treated sarcoma bearing mice (data not shown)." (PMID 23326300, 2013). "We were intrigued by the profound effects that CD4+ T cells had on CD8+ T cell-dependent protective immunity against MCA sarcomas that do not express MHC-II proteins, and therefore decided to study the interdependency between MHC-I and MHC-II neoAg responses in promoting antitumour efficacy." (PMID 39048822, 2024). "For the sarcomas, the expression level of SMC4 was related to the infiltration levels of B cells (r = 0.182, P = 4.65e-03) and CD8+T cells (r = 0.186, P = 3.91e-03), negatively related to the infiltration levels of CD4+ T cell (r = −0.218, P = 7.00e-04) and macrophage (r = −0.14, P = 3.18e-02)." (PMID 36719264, 2023). "Previous studies have found that CBXs were related to the infiltration level of immune cells in CRC and sarcoma, such as CD8+ T cells, CD4+ T cells, CAFs, myeloid dendritic cells, macrophages and B cells, indicating that CBXs might be involved in the regulation of the TME." (PMID 36140750, 2022). "In a sarcoma model using anti-CD3 activated TDLN, CD8 cells caused tumor regression while CD4 cells did not result in tumor regression but instead provided a helper function to CD8 cells that could be replaced with exogenous IL-2." (PMID 26090481, 2015). "Additionally, the combination of HNF1B expression and CD4+ T cell infiltration levels showed prognostic value in cervical squamous cell carcinoma (CESC), brain lower grade glioma (LGG), pancreatic adenocarcinoma (PAAD), rectum adenocarcinoma (READ), sarcoma (SARC)." (PMID 33173410, 2020). "Moreover, the reduction in CD4+ T cells and IFN-γ production observed in this study could also indicate that phosphorylation of tyrosine residues did not occur in HOXA10 to inhibit myeloid differentiation but impeded lymphoid differentiation in the sarcoma patients." (PMID 36005179, 2022). "This sarcoma TME study did not include SFTs in the series, which may explain the discrepancy between their results and the absence of correlations of CD4+ and CD8+ TILs with RSS, as well as variables with prognostic significance and age in our series." (PMID 39335193, 2024). "Interestingly, mIF images from on-treatment tumor biopsies of two progressors with CD8 conversion (sarcoma [ID: 020] and prostate [ID: 023]) revealed an influx of CD8 T cells (>15%) while simultaneously lacking infiltration of B cells and CD4 T cells, or T cell co-expression of TCF-1 and PD-1." (PMID 39190534, 2024). "Considering that sarcoma TIL cultures showed successful expansion and proliferation in vitro, it is likely that the subsets of CD4+CD69+ T-cells and CD8+HLA-DR+ T-cells did not impose suppressive actions and that the markers may be indicative of an activated T-cell population." (PMID 35158816, 2022).